FZD3 (frizzled class receptor 3)
Diseases named in the same sentence as FZD3 in open-access papers (continued):
Sharing a sentence is not in itself a finding about the gene and the disease.
cancer (continued). "The PPI network analysis with cancer-related terms defined six proteins: TGFBR2, TGF-alpha, FGF21, SMAD4, TGFBR1, and FZD3, most of which are involved in tumor development." (PMID 35999337, 2022). "However, the positive staining in only 17% of HCC and 12% of RCCC shows that FZD3 protein may not be so essential in the metastatic process of those 2 carcinomas." (PMID 24255701, 2013). "The PCP pathway, mediated by FZD3 and FZD6, further amplifies non-canonical Wnt signaling’s role in cancer progression." (PMID 40376615, 2025). "The structural versatility of FZD receptors, particularly FZD3, FZD5, and FZD6, enables their interaction with non-canonical Wnt ligands such as Wnt5a and Wnt11, which are often overexpressed in cancers, including breast, colorectal, and melanoma." (PMID 40376615, 2025).
tumor (26 papers, 2008 to 2025). "Analogous arrangements were observed in BCC, with Wnt5a being most strongly expressed at the leading edge, as well as in tumor-associated stroma, while Fzd3 showed polarised expression within the tumor (top middle), or in Fzd3-positive nests (white arrow heads)." (PMID 22384081, 2012). "To validate this result, we further performed TCGA analysis with TCGA-COAD and TCGA-READ datasets and found FZD3 gene was up-regulated in tumor tissues compared to normal ones, with a Log FC that correlates with the result of our datasets." (PMID 37466730, 2023). "FZD3 gene expression is high in metastatic tumours compared to primary tumours and this trend is supported by the literature." (PMID 37958607, 2023). "ICC staining of a tissue section allows us to examine the individual cell under microscope and therefore the FZD3 protein expression in tumor and normal cells can be separately quantified." (PMID 24255701, 2013). "In reality, the ICC staining of FZD3 protein was not only stronger in the invasive front than in the tumor center but also very intense in all metastatic lymph nodes and distant organs." (PMID 24255701, 2013). "By contrast, Fzd3 localized to cells within the tumor mass, sometimes forming nest-like Fzd3-positive tumor-domains (white arrow head) and exhibiting focally polarised intracellular distribution." (PMID 22384081, 2012). "The Wnt5a-triggered bundling of its receptor Fzd3 provides evidence of Wnt5a concentration gradients projecting into the tumor." (PMID 22384081, 2012). "In those tumor cells that did express Fzd3, Fzd3 exhibited a pronounced polarised focal intracellular aggregates, suggesting the existence of Wnt5a gradients." (PMID 22384081, 2012). "These correlations are weaker in tumor tissues, particularly with FZD3." (PMID 32403323, 2020). "The strong expression of Wnt5a at the leading edge, as well as in tumor-surrounding stroma cells, in conjunction with the polarised expression of Fzd3 within the tumor mass suggest that Wnt5a gradients project into the tumor to enhance motility in distinct subpopulations." (PMID 22384081, 2012). "We next studied the spatial relationship of Wnt5a, Fzd3, and Fzd5 in individual tumor samples." (PMID 22384081, 2012). "The present data (strong expression of Wnt5a at the edge and in surrounding stroma, focal polarised intracellular distribution of Fzd3 within the tumors) suggests the existence of Wnt5a gradients acting from the tumor margin (as well as Wnt5a expressing stroma cells, fig." (PMID 22384081, 2012). "Furthermore, we have shown that the FZD3/6/7-mediated signalling is supported by HCC cells within tumour liver tissues." (PMID 18577996, 2008). "FZD3/6 may, therefore, provide an indication of the degree of Wnt ligand signalling in the tumour." (PMID 20628379, 2010). "One study showed that 5′-tiRNAVal, as a new tumor suppressor, can directly target the 3′-UTR sequence in frizzled class receptor 3 (FZD3) and inhibit the FZD3-mediated Wnt/β-catenin signaling pathway in BC cells." (PMID 40565284, 2025). "WNT7A-FZD6/FZD3+LRP6/LRP5, critical components of the canonical Wnt signaling pathway, were exclusively expressed in STAR + cells and tumor cells." (PMID 40098624, 2025). "Increased expression levels of c-myc and FZD3 were less common in FAP (35 and 46% respectively) than sporadic tumours (78 and 67% respectively)." (PMID 20628379, 2010). "The correlation between NKD1, FZD3 and FZD6 and β-catenin stabilisation indicates a cell autonomous effect in the tumour epithelium." (PMID 18414471, 2008). "However, expression of FZD3 didn't show significant difference between GBM and the adjacent non-tumor tissues." (PMID 27852064, 2016). "However, the expression level of target genes, including HMGA2 and FZD3, in tumor tissues was overexpressed in comparison to the normal tissues (p < 0.01)." (PMID 35488374, 2022). "Tumor-infiltrating fibroblasts and endothelial cells were negative for Fzd3." (PMID 22384081, 2012).
infection (2 papers, 2016 to 2017). The state of being infected such as from the introduction of a foreign agent such as serum, vaccine, antigenic substance or organism. "To test whether PCP pathway components are involved in A–P guidance of corticospinal axons, we designed and packaged short hairpin RNA (shRNA)-expressing lentivirus targeting Ryk, Vangl2, Fzd3 or Dvl1 for in vitro infection studies." (PMID 28660073, 2017). "The expression of FZD3, NHS, NOG and TSPAN12 differed significantly between the two pools of cells following infection." (PMID 26837541, 2016).
hematological malignancies (1 paper, 2019). "In hematological malignancies, Circ-CBFB is overexpressed in CLL and is a sponge of miR-607, which promotes CLL cell proliferation but suppresses cell apoptosis via activating FZD3 and the following Wnt/β-catenin pathway." (PMID 31601173, 2019).
peripheral neuropathy (1 paper, 2019). A disorder affecting the peripheral nervous system. "The first GWAS on paclitaxel-induced peripheral neuropathy identified three novel genes important in neurite growth during development (EPHA5 and FZD3)." (PMID 30909387, 2019).
FZD3 also shares sentences with these, for which no sentence is quoted: prostate carcinoma (2 papers); Alzheimer disease (1); Anxiety (1); bipolar disorder (1); cerebrovascular diseases (1); craniorachischisis (1); cyst (1); dementia (1); depression (1); diabetes (1); embryonal carcinoma (1); glioblastoma (1); Headache (1); hepatocellular carcinoma (1); Hyperglycemia (1); male infertility (1); Mcc (1); metastatic renal clear cell carcinoma (1); metastatic tumor (1); myocardial infarction (1); nasopharynx carcinoma (1); Obesity (1); Paranoia (1); small cell lung carcinoma (1); squamous cell carcinoma (1); stomach carcinomas (1); Tension-type headache (1); ulcerative colitis (1).